OSGEPL1 (O-sialoglycoprotein endopeptidase like 1)
Description:
Required for the formation of a threonylcarbamoyl group on adenosine at position 37 (t(6)A37) in mitochondrial tRNAs that read codons beginning with adenine. Probably involved in the transfer of the threonylcarbamoyl moiety of threonylcarbamoyl-AMP (TC-AMP) to the N6 group of A37. Involved in mitochondrial genome maintenance.
Synonyms: Qri7; OSGEPL
Tractability: PROTAC: ubiquitination databases record sites on it.
Gene: Protein-coding gene on chromosome 2 (189,746,415 to 189,763,230, reverse strand). Ensembl gene ENSG00000128694.
Subcellular location: Mitochondrion
Subcellular location (Human Protein Atlas): Mitochondria
Pathways (Reactome):
Metabolism of RNA: tRNA modification in the mitochondrion
Gene Ontology:
Molecular function: tRNA N(6)-L-threonylcarbamoyladenine synthase activity; acyltransferase activity, transferring groups other than amino-acyl groups
Biological process: tRNA threonylcarbamoyladenosine modification; mitochondrial tRNA modification
Cellular component: mitochondrion; mitochondrial matrix
Genetic constraint (gnomAD): Loss-of-function variants: 24 observed, 35.76 expected, observed/expected ratio (o/e) 0.67, 90% interval 0.49 to 0.94. The upper end of that interval is the gene's LOEUF score, 0.94, which puts it in group 4 of 6, group 1 being the genes least tolerant of losing a copy. Missense variants: 374 observed, 476.35 expected, observed/expected ratio (o/e) 0.79, 90% interval 0.72 to 0.86. Synonymous variants: 131 observed, 160.35 expected, observed/expected ratio (o/e) 0.82, 90% interval 0.71 to 0.94.
Homologues: Orthologues: chimpanzee OSGEPL1 (99% identical), macaque OSGEPL1 (97% identical), rabbit OSGEPL1 (88% identical), pig OSGEPL1 (87% identical), guinea pig OSGEPL1 (87% identical), mouse Osgepl1 (85% identical), rat Osgepl1 (82% identical), dog OSGEPL1 (79% identical), zebrafish osgepl1 (60% identical), tropical clawed frog osgepl1 (59% identical), Drosophila melanogaster Tcs4 (40% identical), Caenorhabditis elegans C01G10.10 (32% identical). Paralogues in human: OSGEP (23% identical).
Diseases named in the same sentence as OSGEPL1 in open-access papers:
OSGEPL1 is named in the same sentence as 6 diseases in open-access papers, as found by Europe PMC text mining. Sharing a sentence is not in itself a finding about the gene and the disease. The quoted sentences say what the papers report.
MERRF (1 paper, 2022). A mitochondrial encephalomyopathy characterized clinically by a mixed seizure disorder, myoclonus, progressive ataxia, spasticity, and a mild myopathy. "Deletion of YRDC and OSGEPL1 causes mitochondrial dysfunction (interferes with protein synthesis and respiratory activities) and is clinically associated with an onset of myoclonus epilepsy with ragged-red fibers (MERRF)." (PMID 36362385, 2022).
multiple myeloma (1 paper, 2021). "High expression of LONP1 and OSGEPL1 (O-sialoglycoprotein endopeptidase-like protein 1) in multiple myeloma cells were both associated with more aggressive outcomes and a 1.9- and 1.8-fold shorter median survival, respectively." (PMID 33671345, 2021). "To better understand the transcriptional networks in which LONP1 and OSGEPL1 function, we analyzed the genome-wide co-expression relationships of these two genes in multiple myeloma cells of 747 patients." (PMID 33671345, 2021).
neurological diseases (1 paper, 2022). "Pathogenic mutations of YRDC, OSGEPL1 and KEOPS are implicated in a number of human mitochondrial and neurological diseases, including autosomal recessive Galloway–Mowat syndrome." (PMID 36362385, 2022).
OSGEPL1 also shares sentences with these, for which no sentence is quoted: cancer (2 papers); myoclonus epilepsy (1); tumor (1).